TNF (tumor necrosis factor)
Diseases named in the same sentence as TNF in open-access papers (continued):
Sharing a sentence is not in itself a finding about the gene and the disease.
tumor (continued). "Of significance, the expression of coinhibitory receptors (PD1, KLRG1, LAG3, and TIM3) was considerably lower in CD8+ T cells retrieved from B16 Mgst1 KD tumor, and there was an increase in cytokine response (IFNγ and TNFα) along with Granzyme B." (PMID 37321450, 2023). "IL-2, IFN-γ, and TNF-α are key cytokines that play pivotal roles in the immune response to cancer by activating various immune cells and promoting tumor cell apoptosis." (PMID 37958581, 2023). "In examining select cytokines in the core and edge regions, we observed an elevation in TNF-α, IL-1β, and IL-6 in the edge compared to the tumor core." (PMID 37752585, 2023). "TNFα elicits antigen-independent killing of tumour cells by CD8+ T cells and NK cells, and can directly induce target cell death through signalling." (PMID 37455828, 2023). "Tumor-derived proinflammatory cytokines like IL (interleukin)-6, IL-8, VEGF, tumor necrosis factor-α, and interferon-γ can be secreted into the tumor microenvironment, leading to chronic inflammation, thus facilitating tumor progression." (PMID 36600256, 2023). "Upon stimulation by NK cell-secreted IFN-γ and TNF, these monocyte-derived DCs efficiently present tumor-derived antigens, thereby promoting the activation of tumor-reactive CD8+ T cell responses." (PMID 38022497, 2023). "TNF-α is a tumor-induction factor that induces the production of reactive oxygen species and promotes DNA damage, thus inducing the carcinogenicity of cell." (PMID 37081884, 2023). "In parallel, the other four pro‐tumour molecules showed a consistent pattern similar to TNF‐α or LTβ." (PMID 37997519, 2023). "It was reported that 24 h coculture of bone marrow MSCs pre-stimulated with 10 ng/ml TNF-α for 48 h with MDA tumor cells, induced tumor cell apoptosis via the intercellular interaction with TRAIL on the membrane surface of hMSCs." (PMID 36814921, 2023). "The bestowal of EVs upon CD8 + T cells culminates in their enervation and the concomitant suppression of tumor immunity, as evinced by a substantial reduction in the expression of TNF-α, IFN-γ, granzyme-B, and perforin." (PMID 38087360, 2023). "In general, macrophages can differentiate into proinflammatory classic activated M1 macrophages, which can secrete proinflammatory cytokines such as IL-1, IL-8, IL-12 and TNF-α, mediating inflammatory response and anti-tumor immunity." (PMID 37151385, 2023). "More specifically, TNF-α plays a crucial role in cell survival, proliferation, tumor-promoting, aggressiveness, macrophage infiltration, CAF phenotype, inflammatory chemokine expression, and angiogenesis in BC." (PMID 37895012, 2023). "In this regard, irradiated tumor-cell-derived EVs containing large amounts of DAMPs increased the expression of iNOS, IL-1, IL-6, IL-12, TNF-α and IFN-γ and modified the TME." (PMID 37175226, 2023). "Immunohistochemical (IHC) staining and tumor-infiltrating lymphocyte (TIL) analysis of tumor tissues showed significantly higher densities of activated (IFN-γ- or TNF-α-positive) cytotoxic T cells in the SCCNV-immunized group." (PMID 36854774, 2023). "CNV was positively correlated with the expression of NRGs except FASLG, RIPK3 and TNF in most tumours." (PMID 36583248, 2023). "In normal tissues, TNF+ Tregs account for approximately 1% of Tregs, whereas in tumor tissues, TNF+ Tregs account for approximately 33% of Tregs." (PMID 37534250, 2023). "Despite tumor IFN-γ responsiveness, tumor cell sensitivity to TNF-α influences tumor resistance to CTL attack." (PMID 37732732, 2023). "Previous studies have suggested that high doses of TNFα administered directly into the tumor induce tumor necrosis." (PMID 36996146, 2023). "The M1 macrophages showed accelerated migration towards tumor tissue, increased secretions of TNF-α, ROS, and NO, and enhanced cytotoxicity." (PMID 38001420, 2023). "M1 macrophages possess the tumor-killing activity and are characterized by the production of tumor necrosis factor (TNF) and IL-6." (PMID 36918768, 2023).
tumor (continued). "Although NF-κB p65 (RelA) and TNFα expression levels varied depending on the type of tumor, we found that the GBM exhibited an association between NF-κB p65 (RelA) and TNFα expression levels and overall survival time (OS)." (PMID 37892820, 2023). "In our experimental setting, we found that TAMCs release an increased amount of the pro-inflammatory cytokines IL-6 and TNF- α comparing to MC in tumor-free tissue, suggesting a pro-tumorigenic activity." (PMID 37730723, 2023). "Increased secretion of interferon γ (IFN‐γ), interleukin (IL)‐2, and tumor necrosis factor α (TNF‐α) was measured in B7H3‐redirected BiTE‐T cells cocultured with B7H3‐positive tumor cells (A375, MV411, SKOV3, and THP‐1)." (PMID 36403209, 2023). "The fact that the robust TNFα‐induced invadopodia formation could be observed only in EBV‐positive NPC cells suggests that an EBV‐encoded component plays a crucial role in responding to the inflammatory tumor environment and governing the invasive properties of NPC cells." (PMID 36420735, 2023). "Depletion of murine TNFα significantly abrogated the anti-tumor effect and survival benefit (24 days vs 33 days) of the combination therapy." (PMID 37055579, 2023). "Functionally, NO and TNF-α are not only effector molecules of tumor and microbial immunity, but are also regulatory molecules of a variety of immune cells, acting as important immune regulatory molecules in the body." (PMID 37446941, 2023). "Subsequently, the DCs are mixed with IL‐1β, IL‐6, TNF‐α for 16 to 20 hours and pulse them with tumor antigen to allow antigen uptake and presentation by the DCs." (PMID 36464889, 2023). "These ingredients can potentially decrease the levels of inflammatory cytokines (such as IL-6 and TNF-α), inhibit the expression of tumor-related factors (such as JAK2/STAT3, MMP-9, and vimentin), and increase immune cell activity." (PMID 37742025, 2023). "TNFα is highly expressed in CT26 strains and human CRC, and the anti-tumor effect is enhanced upon administering anti-TNFα mAb in combination with oxaliplatin and 5-fluorouracil." (PMID 36996146, 2023). "We reasoned that this would create a potential selection pressure to lose TNF-α expression to avoid initiation of the anti-tumor T cell response." (PMID 37043573, 2023). "Mechanistically, SIRT7 selectively activated the IRE1α-XBP1 axis to potentiate the pro-survival ERK signal pathway and the secretion of tumor-promoting cytokines like IL-8, TNF-α and VEGFA." (PMID 36918544, 2023). "They showed that such a pre-activation cocktail promoted the proliferation of γδ T cells and their secretion of IFN-γ and TNF-α, which can promote the anti-tumor function of endogeneous CD8+ T cells in vivo." (PMID 38274800, 2023). "Under these conditions, as the first molecule of the inflammatory response, TNF-α enhances the anti-tumor capacity of MSCs." (PMID 36814921, 2023). "M1 macrophages generally contribute to tumour cell destruction by either engulfing or by releasing cytotoxic factors and pro-inflammatory cytokines IL-6, IL-12 and TNF-α." (PMID 37612278, 2023). "The immune responses induced by bacterial cells colonizing in tumors were evaluated by measuring the levels of the proinflammatory cytokines, including IFN-γ, TNF-α, and IL-1β, in the tumor tissues." (PMID 36832032, 2023). "In general, cytokines involved in type 1 immunity including IFNγ, IL-12, and TNFα are shown to orchestrate anti-tumour immune responses against a broad range of cancer types in numerous preclinical and clinical studies." (PMID 37455828, 2023). "Multifunctional CD8+ T cells, as the critical effector cells of protective immunity, can secrete various cytokines (IFN-γ, TNF-α, IL-2, etc.), playing an important role in the anti-tumor effect." (PMID 37542081, 2023). "Previously, we observed elevated blood levels of TNFα, an inflammatory cytokine, in AX cell-bearing mice and reported that TNFα knockout significantly suppressed tumor formation and death from malignancy in these mice." (PMID 38062130, 2023).
tumor (continued). "Recently, it was reported that inhibiting the SREBP pathway prevents HCC by downregulating tumor-promoting cytokines, including IL-6, TNF-α, and IL-1β." (PMID 37434430, 2023). "PD-L1 is up-regulated in tumor cells when TNF-α activates the NF-κB signaling pathway, increasing expression of the IFN-γ receptor (IFNGR1 and IFNGR2)." (PMID 37397393, 2023). "Firstly, the biological functions of natural macrophages highly rely on the pro-inflammatory cytokines, such as tumor necrosis factor α (TNF-α) and interleukins (ILs), which can mediate tumor apoptosis and antitumor immunity." (PMID 37737506, 2023). "The compound also induced T cell co-stimulatory molecules (CD28; CD40L; OX40; CD38), generating overall a marked anti-tumor activity with enhanced IFNγ, IL-2 and TNF expression." (PMID 37296860, 2023). "TNFα can stimulate fibroblast activation in some circumstances, but it is also known to be suppressed by the tumor-promoting immunosuppressive activities of FAP+ fibroblasts." (PMID 36793444, 2023). "It regulates oncogenes, tumor suppressor genes, and angiogenesis factors such as tumor necrosis factor-α, thereby playing an important role in tumor proliferation, migration and distant metastasis." (PMID 37370843, 2023). "Apart from their helper functions, CD4+ T cells can directly kill tumor cells through the release of granzyme B and perforin or by secreting effector cytokines such as tumor necrosis factor (TNF)-α or interferon (IFN)-γ." (PMID 36980536, 2023). "Immunomodulatory cytokines and systemic inflammatory markers (neutrophils, lymphocytes, interleukin-1, 6, 8, 9, and tumor necrosis factor-alpha) in the tumor microenvironment play an important role in tumor formation, invasion, and metastasis." (PMID 36511609, 2023). "Two studies implanted TNFerade biologic, which enables tumour-specific delivery of TNF-α by radiation-inducible gene transfer." (PMID 37254902, 2023). "Common cytokines include TNF-α, IL-6, IL-8, and IL-10, which have the effect of promoting tumor invasion, growth, and angiogenesis." (PMID 37398678, 2023). "TNFα induces expression of C-met, upregulating the recruitment of anti-tumour neutrophils, which kill tumour cells through neutrophil extracellular trap (NET) release, apoptosis, and phagocytosis." (PMID 39935547, 2023). "Stimulating toll-like receptor 4 through lipopolysaccharide can augment the expression of cytokines, such as TNF-α, IL-6, and IL-10, and exacerbate TAMs to polarize toward M2, thus affecting tumor cell invasion and angiogenesis." (PMID 37345200, 2023). "CMC controls tumor growth and increases immunity in the living body by increasing the serum levels of IL-2 and tumor necrosis factor-α (TNF-α)." (PMID 38202616, 2023). "The tumor upregulated pro-inflammatory cytokines TNF-α, MCP-1, and IL-6 when compared with the sham group." (PMID 37174010, 2023). "TNF-α production by peripheral blood T cells in patients with inflammatory breast cancer was positively correlated with the detection of circulating tumor cells expressing EMT markers." (PMID 36835413, 2023). "Further in vitro experiments revealed that IFNγ + IL1β/TNFα increased the elongation and migration of treated tumor cells." (PMID 37169743, 2023). "Mast cells through releasing IL-1, IL-4, IL-6, and TNF-α can actively participate in the elimination of tumor cells and rejection of tumors." (PMID 36793597, 2023). "Matrix metalloproteinase-9 (MMP9) was upregulated by macrophages in response to TNFα and interleukin 1β enriched in the tumor microenvironment DM secondary to PDAC." (PMID 36769405, 2023). "TNF-α, an antitumor cytokine at high concentrations, can also promote tumor growth at low concentrations." (PMID 37208386, 2023). "Since it was first discovered as a cytotoxic agent for tumor cells, TNF is known as a potent mediator in the apoptotic processes in general and as regulator of the immune response, and has been demonstrated to be involved in the pathogenesis of human diseases." (PMID 37242611, 2023).
tumor (continued). "TNF-α not only facilitates tumor initiation but it also promotes tumor cell survival and proliferation via NF-κB activation." (PMID 36845555, 2023). "TNF-α has potent anti-tumor and anti-infection effects at normal concentrations, while excessive TNF-α production can lead to organ dysfunction or death." (PMID 37342357, 2023). "By contrast, macrophage subclusters derived from the chemotherapy-sensitive group were enriched in immune and anti-tumor-related pathways (‘IL-17 signaling pathway’ and ‘TNF signaling pathway’)." (PMID 36725186, 2023). "Among DCIN, tumor necrosis factor (TNF) is a pro-inflammatory cytokine produced and secreted by cytotoxic lymphocytes upon tumor target recognition." (PMID 37033970, 2023). "Flow cytometry analysis showed that PV-1 increased the numbers of CD8+ tumor-infiltrating lymphocytes (TILs) and increased the production of granzyme B, TNF-α, and IFN-γ by CD8+ TILs." (PMID 38077406, 2023). "To dissect tumor-promoting functions of TNF-α, we performed an in vitro proliferation/viability assay using primary WT-GSC cultures." (PMID 37012245, 2023). "The level of TNFα is significantly elevated in the serum of BC patients, and TNF-α is used clinically as a marker for tumor extension and outcome of BC." (PMID 37208442, 2023). "These cytokines, such as IL-6, IL-17, and TNF-α, directly promote tumorigenesis, tumor cell proliferation, angiogenesis, metastasis, and cell death." (PMID 38075864, 2023). "TME, known as an important prognostic marker in cancer patients, features with various pro-inflammatory cytokines including tumor necrosis factor-α (TNF-α), IL-1β and IL-6 to build a tumor-supportive microenvironment to escape immune surveillance." (PMID 37047623, 2023). "M1 macrophages can secrete pro-inflammatory cytokines such as TNF-α to inhibit tumor growth, whereas M2 macrophages can secrete anti-inflammatory cytokines like TGF-β, promoting tumor growth, angiogenesis, metastasis, and invasion." (PMID 37958903, 2023). "It has been shown that BV reduces MMP-2 and MMP-9, decreases VEGF, tumor necrosis factor (TNF) and nitric oxide (NO) levels leading to suppressing tumor proliferation and inhibiting angiogenesis in the Ehrlich ascites carcinoma mouse model." (PMID 37509375, 2023). "TNF-α (also named TNF, cachexin, and cachectin) has been implicated as a large player in several inflammatory, infectious, metabolic, and neoplastic diseases." (PMID 36980727, 2023). "Using flow cytometry, PV-1 was found to induce significant decreases in the frequencies of both splenic and tumor g-MDSCs, resulting in increased expression of granzyme B, TNF-α and IFN-γ by CD8+ cells." (PMID 38077406, 2023). "TNF-α secretion in the tumor region was decreased by FMN/CAL, and NOS2 expression in tumor tissues and cells were also decreased." (PMID 37298670, 2023). "Yet, TNFα production by cDC1s upon PolyI:C was unaffected by tumor cells, even though we observed a trend of tumors with a positive impact to increase TNFα production in a TLR independent manner." (PMID 36891308, 2023). "TNF-α was initially described as a material exerting a necrotic effect on tumor cells (hence the name)." (PMID 37441072, 2023). "TNFα production in OC leads to increases in IL6, VEGF, C-C motif ligand 2 (CCL2), and C-X-C motif chemokine ligand 12 (CXCL12), and lower levels of TNF-α lead to a reduction in tumor growth." (PMID 37445860, 2023). "ABX significantly impaired the therapy efficacy to retard the tumor growth through reduced CpG-ODN–induced TNF expression and decreased the frequencies of TNF-producing cells." (PMID 37361202, 2023). "Significantly increased mitogenic cytokine IL6 and TNF levels were noted in advanced fibrosis, leading to a propensity towards cancer by regulating immune cells and the growth of tumor cells." (PMID 37628834, 2023).
tumor (continued). "Some studies have shown that the sustained high expression of TNF-α can promote tumor growth and invasion, and patients with high expression of TNF-α usually have high metastasis and recurrence rates." (PMID 36992837, 2023). "Current data indicates that combination of SMAC mimetics with anti-tumor T cells can result in combinatorial tumor cell killing through sensitization of tumor cells to TNFα." (PMID 37138866, 2023). "Results of qPCR performed using this mRNA showed that the levels of proinflammatory cytokines, including IL-1β, IL-6, and TNF-α were significantly increased in tumor-bearing mice after DSF treatment." (PMID 37305383, 2023). "HGC-27 cells stimulated by the supernatant of TNF+ Tregs in GCs had significantly increased tumorigenicity and tumor weight." (PMID 37534250, 2023). "Many proteins impact CCL2 expression in tumor cells (e.g., inflammatory mediators such as interleukin-1, interleukin-6, tumor necrosis factor-alpha (TNFα) or transforming growth factor-β (TGFβ))." (PMID 37176074, 2023). "Such an approach should take into account the need to reprogram MCs in order to release anti-tumor mediators (i.e., TNFα) only when in contact with tumor cells to avoid the systemic delivery of unwanted molecules, allergic reactions, or other side effects." (PMID 37376140, 2023). "In this study, we performed single-cell sequencing of gastric cancer and adjacent tissues and found a subpopulation of TNF+ Tregs in GC tumor microenvironment." (PMID 37534250, 2023). "Tumor necrosis factor-α (TNF-α) is a small molecule protein primarily secreted by monocytes and macrophages, that can kill tumor cells and cause apoptosis." (PMID 37382733, 2023). "Considering the protective effect of antioxidants against cancer and the pro-tumor effects of TNF-α, this scenario represents a disbalance that can stimulate cell proliferation, DNA damage, and immune deregulation, favoring BC development." (PMID 37780419, 2023). "Tumor-associated macrophages regulate inflammation and adaptive immunity by producing TGF-β1 and cytokines (TNF-α and IL-6) and promote angiogenesis and cell proliferation." (PMID 36874003, 2023). "Taken together, these results show that ILKAP deletion enhances tumor killing independently of increasing sensitivity to IFNγ or TNF." (PMID 37732732, 2023). "WAT wasting is driven by combinatorial action of tumor-secreted and/or host-secreted factors, such as tumor necrosis factor-α (TNF-α), interleukin-6 (IL-6) or IL-1β, which are transported through the bloodstream." (PMID 37749321, 2023). "that trigger effective IL-1β/TNF-α-mediated immune responses in the tumor leading to tumor regression are preferred over E. coli." (PMID 36900277, 2023). "In response to tumor cells or other stimuli, in vitro differentiated ieILC1-like cells degranulated more, produced more interferon γ and tumor necrosis factor α, and killed tumor cells more effectively than NK-2 like cells." (PMID 38188682, 2023). "For example, the TNF-α stimuli promote the development of tissue architecture needed for tumor progression, while promoting the expression of other cytokines and factors leading to increased tumor growth and survival." (PMID 38068717, 2023). "Meanwhile, compared with the control group, TNF-α had few effects on VEGFR gene expression in tumor tissues." (PMID 37124061, 2023). "On tumor progression, TGF-β facilitates tumor angiogenesis and metastasis, as well as TNF-α promoting the necrosis of endothelial cells involved in tumor cells migration." (PMID 37762927, 2023). "CD8 T cell cytotoxicity can be mediated by perforin and granzyme B, but IFN-γ is also capable of inducing tumor cell cytostasis and death particularly in combination with TNFα." (PMID 38000024, 2023). "In line with this, CHAC1 deficiency in tumor cells impaired the infiltrations of CD8+ T cells, and expressions of IFNγ and TNFα in CD8+ T cells and CD4+ T cells that were all induced by the combination therapy." (PMID 37553341, 2023).